MYC (MYC proto-oncogene, bHLH transcription factor)
Diseases named in the same sentence as MYC in open-access papers (continued):
Sharing a sentence is not in itself a finding about the gene and the disease.
cancer (continued). "Inhibition of the Wnt/β-catenin pathway has been shown to decrease stemness and tumorigenic potential in cancer cells, and there is evidence that MYC is a mediator of the stemness properties conferred by this pathway." (PMID 27821172, 2016). "MYC, a proto-oncogene, is frequently dysregulated, and is therefore responsible for tumorigenesis in many types of cancer." (PMID 27821810, 2016). "The strongly predicted upstream drivers for the MCF-7 GRIP dataset included mainly cancer drivers (MYC, KMT2A) and cancer associated genes (ATF4)." (PMID 27097319, 2016). "The hypoxia-inducible factor (HIF1α), another key oncogenic TF, is functionally coordinated with c-MYC in controlling metabolic reprogramming in cancers." (PMID 27358718, 2016). "In cancer cells, the genes with the highest affinity for MYC, such as the ribosomal protein genes, are saturated with MYC and are also the most sensitive to its inhibition or reduction." (PMID 27460973, 2016). "Recent findings revealed that the PVT1 lncRNA controls MYC protein stability and they both cooperate to promote cell proliferation in cancer." (PMID 27366943, 2016). "The results clearly implicate S6K1 as a potential key therapeutic target for treating cancers with limited nutrient availability and those driven by the oncogene MYC." (PMID 27385002, 2016). "Specifically, PVT-1 occupies a unique cell context within the 8q24.21 region and was demonstrated to be required for the high MYC protein levels in 8q24-amplified human cancer cells." (PMID 27813492, 2016). "In the primary cancer, Kaplan-Meier analysis showed that c-MYC protein overexpression and nuclear ß-catenin expression were significantly correlated with improved prognosis (P = 0.005 and P = 0.007, respectively), but mRNA overexpression was not (P = 0.258)." (PMID 27619912, 2016). "Recent findings revealed that gain of PVT1 expression was required for high MYC protein levels in human cancer cells." (PMID 27366943, 2016). "We therefore performed Q-PCR and found that drug treatment upregulated the expression of these cancer stem cell-associated genes in all three cell lines, including ALDH1, SOX2, c-MYC, OCT4, and NANOG." (PMID 26506421, 2016). "Hypoxia can induce stem cell markers such as octamer-binding transcription factor 4 (OCT4), NANOG, SOX2, kruppel-like factor 4 (KLF4), c-MYC, and microRNA-302 in 11 cancer cell lines including HCC cells through hypoxia-inducible factor (HIF)." (PMID 27050147, 2016). "First, synthetic lethal interactions are generated by persistent overexpression of MYC in cancer cells and impart therapeutic sensitivity." (PMID 27438153, 2016). "Of interest, MYC is over-expressed in a large portion of human cancers and its function appears to be required for the majority of human cancers." (PMID 27382434, 2016). "The protein c-MYC is involved in growth regulation and cellular metabolism, and c-MYC mutations contribute to cancer development." (PMID 27007654, 2016). "MYC oncoproteins deliver a potent oncogenic stimulus in several human cancers, making them major targets for drug development, but efforts to deliver clinically practical therapeutics have not yet been realized." (PMID 27438153, 2016). "Inhibition of mTOR, Aurora A/B, SAE2, or CDK1 has been shown to induce synthetic lethality in MYC-driven cancers." (PMID 27686855, 2016). "Omomyc has been shown to suppress the growth of several cancer cells through its activity as a MYC inhibitor." (PMID 27105536, 2016). "PVT1 encodes a long noncoding RNA that is often amplified and upregulated along with MYC across multiple cancers." (PMID 27579533, 2016). "Both ribosome protein/RNA and CTPsyn upregulation are seen to be a common feature of a number of MYC dependent cancers, while CTPsyn overexpression has been shown to increase filament abundance and size." (PMID 26889675, 2016).
cancer (continued). "DNA double-strand breaks (DSBs) and subsequent translocation events can position the c-MYC gene under the control of a strong promoter of an immunoglobulin gene, leading to activation and overexpression of the oncogene in certain cancers." (PMID 27532010, 2016). "In order to tolerate oncogenic overexpression of MYC, cancer cells must undergo a major remodeling of metabolic and translational pathways- both of which are regulated by mTOR." (PMID 27438153, 2016). "MYC expression is complex and modulated at multiple levels but becomes deregulated in many human cancers." (PMID 27366943, 2016). "Taken together, these results suggest that KRAS-mutant cancer cell lines expressing high levels of MYC are especially sensitive to microtubule-interfering agents, opening up new avenues for therapeutic intervention." (PMID 27412232, 2016). "Approaches based on the principle of synthetic lethality using MYC-overexpressing cancer cells and chemical or RNAi libraries have been employed to search for novel anticancer drugs, also leading to the identification of several druggable targets." (PMID 27313991, 2016). "Then, we assessed the sensitivity of these SCLC cell lines to a bromodomain inhibitor, JQ1, since the effects of JQ1 on the reduction of MYC and MYCN expression associated with growth inhibition have been reported in several other types of cancers." (PMID 27764802, 2016). "HIF-1 and a deregulated c-MYC in cancer cells cooperatively induce transcription of genes involved in hypoxic adaptation such as genes regulating metabolic reprogramming and angiogenesis." (PMID 27119353, 2016). "We then examined the effect of both siRNAs on in vitro cell proliferation, the expression of MYC, a key regulator of cell proliferation in cancer, and cell cycling." (PMID 27469492, 2016). "It remains possible that the effects of extracellular pH on cancer cell metabolism may be from cell signaling pathways involving pH sensors including the G-coupled protein receptor T cell-associated gene 8 (TDAG8) that has the ability to modulate metabolic drivers such as MYC." (PMID 27438712, 2016). "Cancer cells have high levels of activating histone marks on the MYC locus and concomitant high MYC expression." (PMID 26925584, 2016). "Most (but not all) studies have shown that anti-tumorigenic effect of BRD4 inhibition is through the antagonization of MYC, which is the most well-known oncogene in several cancers." (PMID 27081696, 2016). "Aberrant expression of c-MYC is observed in more than 50% of cancers and it is one of the most amplified oncogenes." (PMID 27358718, 2016). "For these reasons, MYC is widely considered ‘undruggable’, a frustrating limitation for such a well-established driver of cancer." (PMID 27081479, 2016). "Results showing that the FDA-approved drugs chloramphenicol and tigecycline can be used to target MYC-driven cancer cells in vitro prompted an examination of the effect of this treatment in vivo." (PMID 27590350, 2016). "BMI-1 knockout was shown to upregulate DKK1 and to target cancer cells via subsequent downregulation of MYC and CCND1." (PMID 26935956, 2016). "Several oncogenes have been implicated in the upregulation of glycolysis of human cancers, including AKT and c-MYC." (PMID 27231905, 2016). "Cell cycle arrest, differentiation, senescence or cell death have been reported to occur in cancer cells after MYC inhibition, through different molecular mechanisms." (PMID 27105536, 2016). "Uncoupling of this feed-forward loop via perturbations in expression of key proteins including those under the control of mTOR (such as 4EBP1) is a likely mechanism that fuels cancer cell growth and cellular addiction to MYC expression." (PMID 27438153, 2016). "Actually it has been known that c-MYC is a major master regulator that plays important roles in many processes like development and cancers." (PMID 27092944, 2016).
cancer (continued). "In most cases, restoration of miR-22 expression suppresses cancer progression through targeting multiple oncogenic proteins, like proteins involved in MYC and CREB pathways, and exacts therapeutic potential in leukaemic mice model." (PMID 27811373, 2016). "Widespread activation of MYC in a range of tumors and the reversibility of MYC-induced tumorigenesis have made MYC an appealing target for cancer therapy." (PMID 27081479, 2016). "Nearly 50% of human cancers have increased MYC expression, and most human cancers require the function of MYC to survive, rendering MYC an attractive target for cancer therapy." (PMID 27382434, 2016). "To gain insight into the role of the c-MYC:BPTF axis in human cancer, we analysed public omics data sets." (PMID 26729287, 2016). "That particular cancers can be addicted to oncogenic signaling changes induced by aberrant MYC expression is well-established through the use of oncogene-regulated mouse models." (PMID 27438153, 2016). "Our findings thus provided novel fundamental insights into the nutrient control of ribosome biogenesis and cell growth via S6K1 and MYC that has implications for understanding how this process is deregulated in cancer cells." (PMID 27385002, 2016). "MYC is the primary target of BET family inhibition in several cancers, and the underlying mechanism is proposed to involve JQ1 inhibiting MYC by disrupting super enhancers, which are defined as large clusters of enhancers that determine cellular identity." (PMID 27081696, 2016). "In summary, mTOR, PI3K, HIF and MYC are key regulators of cellular metabolism that are frequently altered in cancer, collaborating in both synergistic and antagonistic ways." (PMID 28040803, 2016). "MYC is documented to be involved broadly in many cancers, in which its expression is estimated to be elevated or deregulated in up to 70% of human cancers." (PMID 27684546, 2016). "Nevertheless, both c-MYC and ß-catenin expression in primary cancer were significantly correlated with improved survival in univariate (P = 0.001) and multivariate (P = 0.002) analyses." (PMID 27619912, 2016). "Although c-MYC has been a considered a major target for anti-cancer drug development very little progress has been made at directly blocking c-MYC function." (PMID 27259258, 2016). "These compounds appear to have significant therapeutic value for cancers with high levels of MYC, although some effects are MYC-independent." (PMID 27081479, 2016). "Upregulating MYC in U2OS cells to match the levels seen in cancer resulted in MYC molecules being bound to virtually all promoters." (PMID 27460973, 2016). "We then asked if the Wnt/β-catenin pathway is a contributing factor, as this pathway is known to upregulate MYC in other cancer cell types." (PMID 27821172, 2016). "It is likely that MYC inhibition affects different molecular pathways in cancer cells based on cell types, accumulated genetic alterations, and degree and mode of the inhibition." (PMID 27105536, 2016). "These approaches serve as a foundation for developing novel compounds to pharmacologically target MYC-driven cancers." (PMID 27081479, 2016). "It has been reported that MYC expression is elevated in almost all cancers including both HCC and GBM." (PMID 27409345, 2016). "Accordingly, dysregulation of MYC expression is one of the most common abnormalities in human diseases, being MYC overexpression frequently found in most human cancers." (PMID 28040803, 2016). "We have shown that this pathway can be targeted as a means to therapeutically treat MYC-driven cancers, both in vitro and in vivo." (PMID 27590350, 2016). "MYC is a major driver of cancer cell growth and mediates a transcriptional program spanning cell growth, the cell cycle, metabolism, and cell survival." (PMID 27081479, 2016). "Glutamine metabolism and citrate homeostasis in cancer cells are centrally regulated by the oncogene MYC." (PMID 26760764, 2016).
cancer (continued). "BET bromodomain blockade using small-molecule inhibitors gives rise to selective repression of the transcriptional network driven by c-MYC These inhibitors are expected to be potential therapeutic drugs for a wide range of cancers." (PMID 27827996, 2016). "As the NPM-ALK/STAT3 signaling pathway is not the key contributing factor to the differential expression of MYC, we turned to the Wnt/β-catenin pathway, which has been well documented to upregulate MYC in a variety of human cancers." (PMID 27821172, 2016). "We found that patients with high PVT1 expression levels also showed a significant increase of MYC protein concentration for five cancers, including KIRC." (PMID 27366943, 2016). "Today, it is known that deregulation of MYC genes is a frequent event in animal and human tumorigenesis taking place in more than 50% of all human cancers." (PMID 27313991, 2016). "Genome-wide ChIP-seq analysis reveals that the boundaries of decreased H3K9me2 large organized chromatin K9 modifications (LOCKs) are enriched with cancer-related genes, such as MYC and PAX3." (PMID 27034728, 2016). "It is known that c-MYC also promotes transcriptional pause release and that through this mechanism it amplifies the expression of many genes in cancer as well as in normal cells." (PMID 27119353, 2016). "Overall, mitochondrial respiration and anabolic biosynthesis are promoted by MYC, allowing cancer cells to proliferate in oxygen- and nutrient-sufficient conditions." (PMID 27447861, 2016). "From the cross-cancer alteration analysis under the simultaneous query of MYC, NOLC1, DHX33, and CHD7, a large number of cancers possess alterations in these genes." (PMID 27198694, 2016). "Aside from the expression of its target genes essential for cell cycle progression, the oncogene MYC stimulates cancer growth by re-engineering the metabolic system." (PMID 27447861, 2016). "The Ohio State group, in a recently published article in Cancer (median of 28.5 months follow-up) reviewed the outcome of their treated patients with MYC+ and DH, and they demonstrated that only age and achievement of CR was correlated with better outcomes." (PMID 27115017, 2016). "Both MYC and PVT1 reside in a well-known cancer-risk locus and enhanced levels of their products have been reported in different human cancers." (PMID 27366943, 2016). "Further, MYC is strongly repressed by E1A 1-80 in all eight cancer cell lines derived from different origins, whereas HER2 repression is cell line dependent." (PMID 27382434, 2016). "CDCA7L has been shown to be oncogenic in several cancers, in which MYC physically interacts and induces expression of CDCA7L (refs 8, 9)." (PMID 27882933, 2016). "MYC over-expression in solid human cancers often results from abnormal transcriptional or posttranslational regulation." (PMID 27382434, 2016). "c-MYC deregulation is involved in most human cancers and hypoxia is a main contributor to drug resistance in cancer through different mechanisms." (PMID 27119353, 2016). "MYC is a “master regulator” of two interrelated processes in transformed cells, cellular growth and metabolism, and remodelling of cancer metabolic pathways by MYC is vital for maintenance of a rapid cellular proliferation phenotype in MYC-transformed cells." (PMID 27448979, 2016). "Cancerous inhibitor of PP2A (CIP2A) promotes MYC phosphorylation and activity during intestinal crypt regeneration in vivo and in various cancers." (PMID 29527532, 2016). "It has been found that MYC protein is highlyexpressed in cancer cells because of its interaction with HOXB7with estrogen receptors and from cancer database patients whohave high level of this gene have poor survival rates as comparedto lesser ones." (PMID 28149048, 2016).
cancer (continued). "Aberrant c-MYC expression leads to cancer by the coordinated activation of transcriptional pathways involved in cell division, metabolic adaptation, and survival." (PMID 27827996, 2016). "High expression (i.e. oncogenic) levels of MYC are required for apoptosis, offering a unique opportunity to specifically target cancer cells." (PMID 27590350, 2016). "In the metastatic prostate tumor MYC is downregulated due to STAT3-induced transcriptional suppression, however there are reports indicating that STAT3 can also upregulate MYC in different kinds of cancer through IL6." (PMID 28005952, 2016). "Given the significant enrichment of genes from both the MYC and NF-κB Cancer Hallmark gene sets across several ST induced gene clusters, we examined the MCT1 promoter region [-1000, +100] for MYC and NF-κB binding sites." (PMID 27880818, 2016). "Plasmacytoma variant translocation 1 (PVT1) is a highly conserved lncRNA ~50kb downstream of MYC that has attracted significant attention from the cancer field due to its frequent co-amplification with MYC in several solid tumors." (PMID 27232880, 2016). "This suggests the existence of a potential positive feedback loop for sustaining MYC and integrin activity and strengthens their involvement in cancer progression." (PMID 27014720, 2016). "NDRGs are repressed MYC-dependently in various cancers, but induced under hypoxia because HIF-1 directly activates their promoters and indirectly de-represses them by antagonizing MYC." (PMID 27447861, 2016). "CDKN2A has length as the dominant determinant over amplitude in 6/8 cancers, while all 16 cancer types with MYC, CCND2, TERT, or AKT3 amplifications show low AUCs for both parameters." (PMID 26787600, 2016). "We show here that E1A 1-80 represses MYC in all eight human cancer cell lines examined, whereas HER2 repression by E1A 1-80 is cell-type-dependent." (PMID 27382434, 2016). "It was proposed that CIP2A protein promotes cell proliferation by regulating MYC-mediated gene expression, and it mediates cancer progression through interacting with the AKT-mTOR signaling pathway." (PMID 26894380, 2016). "Despite ubiquitous activation in human cancer, essential downstream effector pathways of the MYC transcription factor have been difficult to define and target." (PMID 27590350, 2016). "Targeting of this pathway by MYC inhibitorsfrom start, can ward off cancer cells and reduces the recurrenceby tamoxifen resistance." (PMID 28149048, 2016). "As MYC has been shown to promote metabolic reprogramming of cancer cells, these findings suggest that the reduced oncogenic potential of 3′ WRE-Mut cells is due to an inability to sustain deregulated cellular metabolism." (PMID 27223305, 2016). "There is wide evidence of a complex crosstalk between HIFs and c-MYC, a transcription factor deregulated in most human cancers." (PMID 27119353, 2016). "For example, MYC is an onco-protein family comprised of c-myc, N-myc and L-myc, all of which contribute to pathogenesis in many human cancers." (PMID 27322142, 2016). "In general, the analysis of polyploid transcriptome explained the evolutionary relation of c-MYC and polyploidy to cancer." (PMID 27655693, 2016). "Our results showed that while MYC was only expressed in a few basal cells in NHPrE1/EV grafts, many more MYC-positive cells were detected in the carcinomas that formed in NHPrE1/AR grafts." (PMID 27611945, 2016). "MYC was also isolated from the avian leukemia- and carcinoma-inducing MH2 virus, which carries in addition the v-mil(RAF) allele encoding a serine/threonine protein kinase." (PMID 27313991, 2016). "A number of studies have suggestedthat MYC-driven cancers are reliant on other genes and pathways, unlikenon-MYC-driven cancers." (PMID 26678268, 2015).